FGFR2 (fibroblast growth factor receptor 2)
Diseases named in the same sentence as FGFR2 in open-access papers (continued):
Sharing a sentence is not in itself a finding about the gene and the disease.
tumor (continued). "Among 100 analyzed nuclei in the tumor tissue, the average RP11-62L18 probe signal corresponding to FGFR2 was 63.91, whereas the average chromosome enumeration probe (CEP) 10 control signal was 2.64, yielding a ratio of 24.2." (PMID 28835367, 2017). "FGFR2 KD decreased most GCSC marker expression, including CD44, but increased c-Myc and Sox2 expression and attenuated tumor growth." (PMID 27107424, 2016). "CD44 knockdown (KD) depleted FGFR2 and other GCSC markers, decreased c-Myc and Sox2 expression, and suppressed tumor growth, whereas CD44 activation led to FGFR2 induction." (PMID 27107424, 2016). "Durable partial and complete regressions were observed in both tumor models that are driven by FGFR2 amplification and fusions (NCI-H716 and SNU-16), and the murine transfected cell line (BaF3/FGFR2)." (PMID 27627808, 2016). "Treatment with PD173074 selectively and potently inhibited growth of FGFR2-amplified GC cell lines (KATOIII, SNU-16, and OCUM-2M), leading to a strong decrease in tumor cells in S phase accompanied by an increase in tumor cells in the sub-G1 population." (PMID 26000013, 2015). "Further, CCND1 can enhance tumor progression, at least in part, by an increased level of transcription of FGFR1 and FGFR2 via E2F." (PMID 25596748, 2015). "On the other hand, a qPCR analysis using mouse-specific primers revealed that the expression of VEGFA, FGF2, FGFR2 and platelet-derived growth factor receptor A (PDGFRA) was upregulated in the bevacizumab-treated tumour stroma." (PMID 26635184, 2015). "In a study of FGF-8 expression in OC, this cytokine was localized to tumor cells, whereas its receptors FGFR1, FGFR2, and FGFR4 were expressed by tumor cells, and to lesser extent, in stromal cells." (PMID 24860785, 2014). "We observed a broad distribution of the fibroblast growth factor receptors FGFR1, FGFR2 and FGFR3 fusions—in particular FGFR3–TACC3 fusions—across eight of the 20 tumour types analysed." (PMID 25204415, 2014). "The FGFR2 fusion partner observed in this patient's tumor, TACC3, is overexpressed in many tumor types with enhanced cell proliferation, migration, and transformation observed in cells overexpressing TACC3." (PMID 24550739, 2014). "Inhibition of AKT upregulated the tumor levels of P-InsR/IGF-IR, InsR, P-HER3, HER3, P-HER2, HER2, the FGFR substrate P-FRS2 and FGFR2 proteins." (PMID 23844554, 2013). "FGFR2 and its isoform are highly expressed in CRC and correlate with CRC growth, invasion, and tumor angiogenesis." (PMID 22701813, 2012). "However, FGFR2 signaling in the tumor setting, where FGF2 and FGF7 are likely available from the surrounding microenvironment, may establish a paracrine pathway leading to continued cancer cell survival, growth and maintenance of transformation in the presence of EGFR targeted therapies." (PMID 21152424, 2010). "Therefore, although there are several studies reporting a tumour-suppressive effect of FGFR2 in a variety of cancer types, including bladder, prostate and skin, it is easy to see how the pathway might be hijacked by cancer cells to provide them with a significant growth advantage." (PMID 19410332, 2009). "While FGFR2-targeted therapies are primarily studied in advanced ICC, this report presents a rare case of locally recurrent ICC treated with systemic therapy, leading to significant tumor regression and successful R0 resection." (PMID 40255433, 2025). "On the other hand, some of them reported lower FGFR2 expression levels in tumor tissues compared to adjacent normal breast ducts." (PMID 40748883, 2025).
tumor (continued). "Notably, FGFR2 fusions were identified in IDH-mutant glioblastomas, a tumor type where the presence of oncogenic FGFR alterations was previously unrecognized." (PMID 41567627, 2025). "Additionally, clinical observations and our own data indicate that high levels of FGFR2 and FGFR3 correlate with advanced tumor stages and poor prognosis." (PMID 41467942, 2025). "Additionally, surufatinib inhibits the activity and secretory functions of CAFs by targeting FGFR2, reducing the accumulation of the ECM, decreasing the rigidity of the tumor microenvironment, and increasing immune cell permeability." (PMID 40376004, 2025). "In GISTs, FGFR2 expression has been reported at variable levels, particularly in tumors lacking KIT or PDGFRA mutations, suggesting a role in tumor progression independent of canonical drivers." (PMID 41150770, 2025). "Together, these properties suggest that the FGFR2::SHTN1 fusion protein may act as a multifunctional oncoprotein, simultaneously driving transcriptional and cytoskeletal programs that promote tumor progression." (PMID 41496852, 2025). "We subsequently investigated the distinctive features of the tumor immune microenvironment of tumors with FGFR2 fusions or rearrangements (FGFR2+ cohort) as compared to tumors without FGFR2 fusions or rearrangements (FGFR2 WT cohort)." (PMID 39969434, 2025). "Furthermore, our database contains receptors including ESR1, FGFR2, and VDR, which are recognised for their roles in cellular responses and tumour development." (PMID 40754672, 2025). "To determine whether AKT3 or FGFR2 can serve as potential targets, we first constructed the F0 generation PDX tumor models with biospecimens from PPLELC patients and transplanted into F1 generation PDXs for efficacy experiments." (PMID 40057671, 2025). "Notably, 42% of the 142 methylation‐regulated tumour genes are controlled by multiple methylation sites, especially MGMT (14 sites), AATK (12 sites), VRK2, and FGFR2 (10 sites)." (PMID 41292185, 2025). "A tumor was not present in some of the tissue cores in the TMA [for FGFR2 (n = 2) and FGFR4 (n = 1)]." (PMID 41228379, 2025). "Similarly, when tumours were HER2-negative (HER2: 0 or 1+), or equivocal (HER2: 2+), the FGFR2 expression levels were similar, but the levels were significantly lower in HER2-positive (2+ with FISH or 3+) tumours." (PMID 39596875, 2024). "A so far unknown FGFR2 fusion, FGFR2-AHCYL2, was detected in the tumor of a young female patient with an exceptional clinical course." (PMID 38346946, 2024). "FGFR2 fusion/rearrangement may exert a profound impact on the prognosis of ICC patients and reprogram the tumor microenvironment to be an immune-activated state." (PMID 38986528, 2024). "More recently, the FGFR2-targeting antibody BAY 1,179,470 has also been developed as a targeted alpha-particle therapy (TAT), which utilizes a monoclonal antibody to deliver an alpha-particle-emitting payload to tumour cells." (PMID 38791079, 2024). "Overall, FGFR2 mRNA levels are lower in HER2+ tumours and higher in hormone-responsive tumours." (PMID 39596875, 2024). "In a phase I/II clinical trial, derazantinib exhibited encouraging anti-tumor efficacy and tolerable safety profiles among patients diagnosed with advanced, unresectable ICC harboring FGFR2 fusion, resulting in a notable response rate of 20.7% and a disease control rate of 82.8%." (PMID 38831455, 2024). "For example, in a phase I study of the oral pan-FGFR inhibitor LY2874455, of 15 GC patients evaluated for efficacy, only one patient had a partial response, and the patient’s tumour was not FGFR2 amplified." (PMID 38791079, 2024).
tumor (continued). "Herein, tumor specimens from 226 ICC patients were collected, and fluorescence in situ hybridization (FISH) and multiplex immunofluorescence (mIF) were performed to understand the immune landscape of ICC cells with different FGFR2 statuses." (PMID 38986528, 2024). "Together, our results strongly support that FGFR1, but not FGFR2, promotes tumor invasion in GBM, linking spatial distribution of receptor expression within GBM to function on cell motility." (PMID 37579831, 2023). "Therefore, we wanted to elucidate if FGFR1 and FGFR2 are expressed in GBM in vivo and if there are receptor-specific patterns of expression, specifically comparing tumor core and invasive areas." (PMID 37579831, 2023). "First, we do not have a long follow-up of these enrolled CC patients to see whether patients with high level of FGFR2 and CEBPB were more prone to develop into tumor." (PMID 36996081, 2023). "We performed statistical analysis on the percentages of CEBPB+ve / FGFR2+ve bile duct cells / parenchymal cells between two groups, either CC vs. HB tumor group; or CC vs. HB non-tumor group." (PMID 36996081, 2023). "We found FGFR1 expressed in tumor mass and infiltrating GBM cells, while FGFR2 expression is confined to the tumor mass and notably absent in diffusely invasive cells." (PMID 37579831, 2023). "In agreement with this, histological sections from FGFR2‐mutant ECs showed that there was a significant increase in apoptosis (as indicated by brown‐stained nuclei) following DPC injection, compared to that of untreated tumours." (PMID 37165578, 2023). "Nonetheless, existing evidence does not support correlations of FGFR2 fusion partners with tumor response to pemigatinib." (PMID 36127767, 2023). "Distinctive positive staining in bile ducts were seen in CC, HB tumor and non-tumor liver tissues for FGFR2 and CEBPB." (PMID 36996081, 2023). "In contrast, the percentages of parenchymal cells that were immuno-positive for CEBPB or FGFR2 were not significantly different between CC and HB tumor and non-tumor livers." (PMID 36996081, 2023). "High expression levels of ABL1, FGFR2, MTOR, BRAF, and PARP1 were seen in both tumor subtypes." (PMID 36991316, 2023). "Moreover, TAX evidently inhibited the tumor growth in nude mice and the expression of c-Myc, cyclin D1, p-AKT and FGFR2 were down-regulated in xenograft tumor." (PMID 37567936, 2023). "We tested the existence of FGFR2 and MET in tumor specimens from different organ sites." (PMID 38137393, 2023). "Since ADAM17 is the subsequent step following FGFR2 activation in migration and proliferation of EC cells, targeting ADAM17 function in FGFR2-mutant cells may have a beneficial effect in tumor suppression." (PMID 37759450, 2023). "Lastly, we tested the existence of FGFR2 and MET in tumor specimens from different organ sites." (PMID 38137393, 2023). "In the tumor xenografts, immunohistochemistry staining demonstrated that TAX treatment decreased the number of Ki67-positive cells and reduced the expression of c-Myc, cyclin D1, p-AKT and FGFR2." (PMID 37567936, 2023). "In addition, we found that FGFR2, FGFR3 and FGFR4 expression was increased in the tumour tissues compared to that in normal tissues in the TCGA_LIHC datasets." (PMID 37846441, 2023). "From this point of view, FGFR tyrosine kinase inhibitors should be more effective than ICIs if the tumors carry FGFR2 alterations because tumors with alterations in the FGFR2 genes generally showed a “non-inflamed” tumor phenotype." (PMID 37190307, 2023). "We identified that the tumour-driver potential of C-terminally truncated FGFR2 is independent of specific fusion partners, whereas full-length FGFR2 overexpression was marginally tumorigenic in the absence of other driver alterations." (PMID 35948633, 2022). "To determine whether CXCL12 participate in FGFR2+ fibrocyte recruitment, we first established whether a CXCL12 gradient existed between ESCC tumor mass and peripheral blood by ELISA." (PMID 35941662, 2022).
tumor (continued). "Comprehensive analysis of The Cancer Genome Atlas (TCGA) RNA-seq data identified tumours expressing FGFR2 in-frame fusions as well as non-canonical REs." (PMID 35948633, 2022). "Notably, in isolated cases, it has been reported that amplification of Fgfr2 occurs in one part of the tumor and amplification of HER2 is detectable in another part of the tumor." (PMID 35167603, 2022). "In particular, we focused on well-established (PD-L1, HER2, and vascular endothelial growth factor receptor 2 (VEGFR2)) and emerging (mesenchymal-epithelial transition (MET), fibroblast growth factor receptor 2 (FGFR2), Claudin 18.2 (CLDN18.2), and tumor-infiltrating lymphocytes (TIL)) biomarkers." (PMID 35327345, 2022). "The analysis revealed high correlation within FGFR1, FGFR2, and FGFR3 expression assessed with both methods (r = 0.77, p = 0.000001; r = 0.86, p = 0.000001; and r = 0.95, p = 0.000001, respectively) in 40 Sq-NSCLC tumor samples." (PMID 36142417, 2022). "To extend these findings, we treated ESCC tumor-bearing mice (induced by either KYSE30 or EC9706 cells) with FGF2 neutralizing antibody for 20 days and analyzed the effects on tumorigenesis and infiltrated FGFR2+ CAFs." (PMID 35941662, 2022). "FGFR2+CD90+ cells were increased slightly after tumor resection (all P < 0.05) but not after ESCC implantation (all P ≥ 0.05)." (PMID 35941662, 2022). "In our study, we found that the FGFR2+ fibrocytes isolated from both ESCC patients and ESCC tumor-bearing mice could be recruited into tumor mass under the stimulation of ESCC cells." (PMID 35941662, 2022). "Consistent with our data, recent evidence in the gastrointestinal stromal tumour cell line T-1R shows that the alternative FGFR1-3 inhibitor BGJ398 (Infigratinib) or knockdown of FGFR2 attenuates DSB repair by HR and not by NHEJ." (PMID 35778553, 2022). "We found that FGFR2+ hematopoietic stem cell (HSC)-derived fibrocytes could be induced by ESCC cells, recruited into tumor xenografts, and differentiated into functional CAFs." (PMID 35941662, 2022). "Here, we aimed to independently validate the expression and putative tumor biological significance of FGFR2 in a large non-Asian GC cohort." (PMID 35167603, 2022). "In terms of FGFR-2 mutation, we found the following correlation p-values: LVI (p = 0.069), expression of vimentin (p = 0.000), tumor budding (p = 0.000), and lack of E-cadherin (p = 0.000), RFS (p = 0.032), ECSS (p = 0.047)." (PMID 36143062, 2022). "Previous studies demonstrated that miR-889 could regulate the tumor cellular behaviors by targeting serval target genes, such as KLF9, SIX1, DAB2IP, TAB1, FGFR2, TWEAK." (PMID 34116691, 2021). "It is demonstrated that FGFR2 suppresses BRCA1 via the ERK‐YY1 axis and promotes tumor progression." (PMID 34514747, 2021). "We found FGFR1 transcript to be selectively elevated in cells from spindloid tumours when compared to all other tumour types and normal mammary gland, while FGFR2 and FGFR3 were not modulated and FGRF4 was undetectable (not shown)." (PMID 33772015, 2021). "The pathways related to tumor progression, such as positive regulation of the MAPK cascade and FGFR (FGFR1, FGFR2, FGFR2c, FGFR3, and FGFR3c) ligand binding and activation, were significantly downregulated in the FSIP2-MT group (ES < 0, p < 0.05), suggesting a better efficacy." (PMID 34113648, 2021). "Since LLC2B could specifically bind to FGFR2-positive cells and was highly stable in human plasma, we then made PDCs of LLC2B conjugated with DM1 to assess their cytotoxic effects on tumor cells." (PMID 34440055, 2021).
tumor (continued). "BMI, treatment indication, biopsy type (pipelle vs. curette), hysterectomy status, FGFR2 protein expression or FGFR2 isoform and PR tumour expression were not statistically significant." (PMID 33916719, 2021). "As BRCA1 suppresses tumor growth, we hypothesized that full BRCA1 dosage might inhibit tumorigenesis, while BRCA1 suppression by FGFR2 signaling could weaken this inhibition." (PMID 34514747, 2021). "In contrast to UC tumor specimens, phosphorylation of members of the FGFR family of RTKs was lower in UC cell lines (FGFR1 25%, FGFR2 25%, FGFR3 25%, and FGFR4 0%) which may reflect the presence of stromal cells within the primary tumor samples evaluated." (PMID 34600548, 2021). "This may lead to enhance FGF/FGFR signaling activities which make the way for FGF9 to promote MA-10 tumor growth, since we observed that FGF9 activated the downstream signaling through FGFR2 in MA-10 cells." (PMID 33172093, 2020). "Furthermore, high expression of FGFR-2 in HCC has been correlated with multiple tumor nodules, distant recurrence, less tumor differentiation, portal vein invasion, a high level of alpha-fetal protein, and poor prognosis." (PMID 33321903, 2020). "Proto-oncogenes are those genes that are involved in cell growth and proliferation, with potential examples including the ATM, FGFR2, FN1, IGF1, MAP3K, MMP7, and RHOC genes, while the CASP8 and LSP1 genes have been reported to possess tumor-suppressive properties in certain types of cancer." (PMID 33112566, 2020). "Tumor over-expressing the mouse VEGFR2 extracellular domain fused with the human IgG4 fragment crystallizable (Fc) region (VEGFR-2-Fc) showed highest levels of mRNA expression from FGF2 and other factors of FGF-2/FGFR-2 pathway." (PMID 32456056, 2020). "The algorithm was successfully taught to recognize cancer cells, tumour stroma and adjacent non-cancerous tissue, and to measure the intensity of FGFR2 cytoplasmic and membrane staining, specifically in cancer cells." (PMID 33297384, 2020). "We also found that the expression of FGFR2-IIIb, but not of total FGFR2, was significantly increased in tumor samples." (PMID 31881796, 2019). "In the FGFR1-amplified lung cancer cell line H1581-xenograft mice and FGFR2-amplified GC cell line SNU16-xenograft mice, oral administration of SOMCL-085 for 21 days substantially inhibited tumor growth without loss of body weight." (PMID 31242658, 2019). "Interestingly, when analyzing exclusively tumor data, ESRP1 expression was significantly increased when the FGFR2 locus was concomitantly deleted." (PMID 31881796, 2019). "Fibroblast growth factor receptor 2 (FGFR2) is considered as a potential therapeutic target in multiple types of cancer since its substantial overexpression has been observed in diverse tumor cells and low level of expression on the surface of non-tumor cells." (PMID 29420662, 2018). "Of note, some tumor cells visible in this image do not show FGFR2 mRNA expression whereas the majority of the cells very strongly express FGFR2." (PMID 28852882, 2018). "Unlike with normal brain tissue, FGFR2 is strongly positive throughout the entire tumor mass, with the fibrovascular supportive stromal tissue and their hyperplastic fibroblasts being weakly positive (see arrows)." (PMID 29038531, 2017). "The ddPCR CNV assay detected the FGFR2 amplification in both metastases but not in the primary tumor or matched normal sample." (PMID 28629429, 2017). "Notably, preclinical results have demonstrated robust anti-tumor efficacies of various FGFR-selective, small-molecule inhibitors such as AZD4547, BGJ398, and LY2874455 in FGFR2-amplified GC cell lines." (PMID 28122360, 2017). "Using next generation sequencing for the 48 TruSeq cancer panel, we identified oncogenic mutations in FGFR2 and ATM genes in the ACC11 cell culture that had not been reported for this tumor." (PMID 28900283, 2017).